TAP1 (transporter 1, ATP binding cassette subfamily B member)
Diseases named in the same sentence as TAP1 in open-access papers (continued):
Sharing a sentence is not in itself a finding about the gene and the disease.
tumor (166 papers, 1994 to 2026). "TAP1 is involved in antigen processing and immune regulation, with its downregulation often linked to tumor immune evasion and poor prognosis, and its upregulation associated with increased ICI response." (PMID 40659866, 2025). "Transporter associated with antigen processing 1 (TAP1) is a transporter protein that presents tumor antigens in the MHC I or HLA complex." (PMID 40535120, 2025). "Transporter associated with antigen processing 1 (TAP1) is a crucial molecule responsible for the processing and presentation of tumor-associated antigens." (PMID 39103807, 2024). "Transporter associated with antigen processing 1 (TAP1) is a molecule involved in the processing and presentation of antigens restricted to the major class I tissue compatibility complex, including tumor-associated antigens." (PMID 39201395, 2024). "Recent studies have shown that TAP1 is closely associated with various tumors and has the potential to become a novel tumor-targeting drug." (PMID 36774490, 2023). "TAP1 is conventionally considered a tumor-associated gene; however, it showed diverse correlations with prognosis in pan-cancer analysis." (PMID 36759763, 2023). "Various studies have demonstrated that mutations or changes in the expression of TAP1 play roles in tumor immune escape and affect tumor progression, while still remain certain controversial in terms of cancer." (PMID 36419887, 2022). "Immune landscape characterization demonstrated the significant association of TAP1 with the tumor immune microenvironment in ccRCC." (PMID 36419887, 2022). "In melanoma tumor cells, CARM1 ablation induced dsDNA breaks and cGAS-STING activation, together with the increased expression of several ISGs, including Irf7, Ifit1, Oasl1, and Tap1, and the enhancement of tumor cell susceptibility to cytotoxic T cells." (PMID 35493527, 2022). "TAP1 is associated with antigen processing of major histocompatibility complex class I peptides for recognition by tumor-specific cytotoxic T lymphocytes." (PMID 35123499, 2022). "TAP1 encodes a transporter that is responsible for presenting tumor antigens in major histocompatibility complex I or human leukocyte antigen complexes." (PMID 34631788, 2021). "While TAP1 upregulation has been linked to better targeting of tumor cells, there is contradictory evidence that shows the overexpression of TAP1 is associated in cancer development." (PMID 34047812, 2021). "TAP1 is responsible for processing exogenous pathogenic microorganisms and then presenting them to immune cells, thereby functioning as a target for tumor cells." (PMID 34957213, 2021). "The expression level of TAP1 was correlated with immune checkpoint genes, DNA methylation, tumor mutation burden, microsatellite instability, and neoantigens in various cancers." (PMID 34957213, 2021). "Using univariate Cox regression survival analysis, we found that low expression of the TAP1 gene in tumor-free samples was significantly associated with better patient survival (p < 0.05 for both overall and disease-free survival)." (PMID 32867395, 2020). "Kaplan–Meier survival analysis showed that low TAP1 in tumor-free tissues was significantly associated with better overall survival (log-rank test, p-value = 0.024)." (PMID 32867395, 2020). "Tumor associated antigens expressed by malignant cells are transported by TAP-1 and TAP-2 into the endoplasmic reticulum and loaded onto MHC-I, then translocate to the cell surface to present to CD8+ CTLs." (PMID 31737100, 2019). "As expected, downregulation of TAP1 in IGR-Heu-TAP tumour cells resulted in an increase in their susceptibility to anti-ppCT16–25 CTL-mediated lysis, while it resulted in a decrease in anti-ppCT9–17, anti-ppCT50–59, anti-ppCT91–100 and CTL-mediated killing." (PMID 30504837, 2018). "The tumor cells express normal levels of TAP1, but a mutation disrupts the peptide transport process." (PMID 29091951, 2017).
tumor (continued). "Another tumor sample presenting a mixed pattern (MEL 22) showed a loss of TAP-1 expression despite HLA class I expression." (PMID 27484791, 2016). "Regarding EC, the loss of expression of MHC class I and TAP1 has been reported to render some tumor cells to escape the immune surveillance and contribute to the clinical course of EC." (PMID 26205887, 2015). "Finally, the association between TAP1 and tumor growth and the immune microenvironment of UVM as well as its mechanism of action would require further investigation." (PMID 36774490, 2023). "Although high TAP1 expression might, in theory, make tumor cells more susceptible to cytotoxic T cell killing, it might reduce their susceptibility to natural killer (NK) cell–mediated lysis." (PMID 36774490, 2023). "However, few studies have proposed associations between TAP1 and responses to therapeutic anti-tumor regimens." (PMID 36759763, 2023). "It has been observed that in a SCLC cell line, the presence of a defective allele in TAP1 causes a change of amino acids, which leads to a defective presentation of antigen; in addition, the restoration of TAP1 activity in tumor cells increases the susceptibility to CTL-mediated killing." (PMID 36015341, 2022). "The high expression of TAP1 may be associated with the production of more tumor neoantigens, which in turn initiate tumor immunity." (PMID 36419887, 2022). "Additionally, we analyzed the correlation between TAP1 expression and tumor mutation burden (TMB) and microsatellite instability (MSI) and tumor neoantigens." (PMID 34957213, 2021). "Additionally, 150 paraffin-embeded tumor specimens and 283 matched cancer-free controls were used to investigate the association between TAP1 polymorphisms and risk of EC in this ethnic and to accumulate evidence regarding the potential role of TAP polymorphisms in the disease." (PMID 26205887, 2015). "At the same time, the expression level of EGFR is negatively correlated with the infiltration of CD8+T cells in tumor tissue and TAP1, which is a transporter to represent tumor antigen in the MHC-I complex." (PMID 39820491, 2025). "However, among the class III gene mutation testing results, the genes with higher abundance mutations include MKNK1, POLE, RET, RTEL1, RUNX1T1, TAP1, indicating that these gene mutations may be related to sex-cord-stromal tumors or require further research to explore unknown tumor subtypes." (PMID 40901169, 2025). "Further studies revealed that the MTDH-SND1 complex binds to Tap1/2 mRNA and promotes its degradation, thereby reducing tumor antigen presentation and inhibiting T-cell infiltration and activation." (PMID 40775338, 2025). "Specifically, diminished STAT1 activation can lead to low HLA class I expression, which impairs the effectiveness of cytotoxic T lymphocyte (CTL) responses in mediating tumor elimination and mediates TAP1-dependent escape from CTL." (PMID 41012104, 2025). "Tumor fragment 5 stood out as the most “immune-hot” region, with elevated expression of B2M, HLA-I/II, TAP1/2, and markers of CD8/CD4 T cell infiltration, which in turn correlated with its high antigen abundances." (PMID 40777321, 2025). "Aberrant expression of TAP1 has been observed in various tumor types and is known to impact multidrug resistance in human cancer cell lines during chemotherapy." (PMID 39103807, 2024). "Consistently, we observed comparable mRNA and protein levels of TAP1/2 between Map3k1-WT and Map3k1-mut tumor cells in the coculture system after silencing Ddx17." (PMID 39531335, 2024). "Compared with PBS control, VC treatment increased the expression of TAP1 in the tumor clusters, but remained largely unchanged between WT and TET2-KO tumors." (PMID 39388288, 2024). "TAP1 becomes a strong tumor prognostic marker that has demonstrated clear prognostic relevance in most cancer types and is also an emerging predictor of clinic prognosis and immunotherapy response among various cancers." (PMID 39296237, 2024).
tumor (continued). "Immune-related proteins were first analysed, and we revealed that IFN-γ increased not only tumour cell PD-L1 but also antigen peptide transporter 1 (TAP1), HLA-A, HLA-B, HLA-C and ICAM-1, indicating strong adhesion and enhanced immunogenicity." (PMID 38719909, 2024). "These core genes contained at least 8 (PPP2R2A, CXCL10, CXCL11, GBP1, IRF1, RARRES3, STAT1, and TAP1) previously identified regulators of tumor progression and distant metastasis." (PMID 38545852, 2024). "Map3k1-mut lost this effect, leading to promoted degradation of Tap1/2 mRNAs in Map3k1-mut compared to Map3k1-WT tumor cells." (PMID 39531335, 2024). "Consistent with the in vitro cell experiments, we observed that PTP 9 and anti-PD-1 cotreatment induced a significant increase in tumor expression of Cxcl11, Ccl5, Stat1, Stat3, Tap1, Irf1, Casp8, and Pdl1, compared with anti-PD-1 treatment alone." (PMID 36968224, 2023). "Confirming screen robustness, sgRNAs targeting genes required for T cell function were depleted from the tumor, including Tap1, B2m, CD47, Jak1, and Jak3." (PMID 38099496, 2023). "Precise therapy targeting tumor immunity based on distinct TAP1 expression levels shows promise for application in cancer patients." (PMID 36759763, 2023). "Scattered TAP1 expression was also detected among all candidate tumor cell lineages; however, levels were lower than those in immune cell lineages." (PMID 36759763, 2023). "Overall, HLA-E and -F coexpression correlated with high levels of HLA-A, TAP1/2 and B2M transcripts across tumor types." (PMID 38318504, 2023). "TAP1 is a robust tumor prognostic biomarker and a novel predictor of clinical prognosis and immunotherapeutic responses in various cancer types." (PMID 36759763, 2023). "To determine TAP1 expression patterns in tumor masses, we further explored the individual expression of TAP1 in immune and malignant cell populations using the TISCH tool." (PMID 36759763, 2023). "Single-cell analyses of TAP1 across cancers were conducted via the Tumor Immune Single-cell Hub website." (PMID 36759763, 2023). "TAP1 also plays a role in tumor development and treatment resistance, mainly by affecting tumor immune infiltration." (PMID 36774490, 2023). "TAP-1 is critical for the major histocompatibility complex (MHC-I) antigen processing pathway and is associated with host-tumor surveillance levels." (PMID 35626709, 2022). "The enrichment of GSEA in immune-related pathways further proved the relationship between TAP1 and tumor immunity, followed by the analysis of the genes related to the interferon pathway." (PMID 36419887, 2022). "Here, our results indicated that the high expression of TAP1 in ccRCC promotes the tumor metastasis." (PMID 36419887, 2022). "The results of experiments in vitro demonstrate the contributive role of high TAP1 expression in tumor migration, suggesting its contribution in metastasis." (PMID 36419887, 2022). "The genes upregulated in MΦ subtypes from tumours treated with topical caerin gel including Stat2, Isg15, Tap1, Psmb9, and Parp9, were more highly expressed in the CCI than CCII MΦs." (PMID 36497272, 2022). "The results of experiments in vitro demonstrated that the high expression of TAP1 contributes to tumor migration, suggesting its role in metastasis." (PMID 36419887, 2022). "The iodine-125 labeled version of TAP1 showed lower, but more rapid tumor uptake, and lower blood levels than [18F]F-TAP1." (PMID 35788730, 2022). "Considering the role of TAP1 in the process of antigen presentation, it potentially has a close relation to tumor immunity." (PMID 36419887, 2022). "The more mechanistic explanations for the functions of TAP1 independently of transporter in tumor progress remain to be established." (PMID 35806187, 2022). "In the mouse xenograft model, the tumor size and weight were significantly increased by the overexpression of TAP1 in AsPC-1 xenograft, compared to the control groups." (PMID 35806187, 2022).
tumor (continued). "Surprisingly, in the analysis of TCGA proteome database, the expression of TAP1 in early ccRCC (stage 1 and 2) was shown increased in line with the increase of tumor stage." (PMID 36419887, 2022). "According to the analysis of various databases, the role of TAP1 in ccRCC was explored, especially in relationship of TAP1 with tumor microenvironment." (PMID 36419887, 2022). "• This study demonstrated, for the first time, a correlation between the TAP1 gene and tumor progression." (PMID 34047812, 2021). "We found ACAP1, IFIT3 and TAP1 were upregulated in tumor samples, while ADAMTS9, COL6A2, FBN1 and FSTL1 were downregulated in tumor specimens." (PMID 34112144, 2021). "An altered TAP1 gene results in an ineffective HLA-1 complex and helps escape tumor detection by the immune cells." (PMID 34047812, 2021). "The study has some interesting findings that can assist in further exploration of the TAP1 gene in oncogenic tissues, its role in cancer progression and tumor immune evasion." (PMID 34047812, 2021). "To further confirm the metastasis-promoting effects of TAP1, we performed in vivo xenograft tumor experiments in nude mice." (PMID 34957213, 2021). "In the case of tumor progression, TAP1-negative cells have been reported to be selection-wise favored over TAP1-positive cells." (PMID 33917061, 2021). "According to the analysis of tumor neoantigen load and immune checkpoint, TAP1 had the potential to become a novel tumor-targeted drug." (PMID 34957213, 2021). "We also analyzed the TAP1 expression for different tumor tissues and their respective counterparts utilizing GENT2 through the HG-U133Plus2 database, and considered two sample t-test p-value of < 0.001." (PMID 34047812, 2021). "This study demonstrated, for the first time, a thorough computational analysis of the TAP1 gene in multiple cancers to find a correlation between the TAP1 gene and tumor progression, using numerous recognized software and databases." (PMID 34047812, 2021). "A significant overexpression for the TAP1 expression was seen in the primary tumor in comparison with the normal in BRCA, LIHC, and LUAD." (PMID 34047812, 2021). "The analytical data presented in the study is vital to learn about the effect of TAP1 in tumor tissue, where previously studies showing contradicting expression of TAP1 in cancer tissue." (PMID 34047812, 2021). "The IFN-y induction results when tumor cells escape targeting and INF-y induces TAP1 to trigger tumor detection as a part of the immune response." (PMID 34047812, 2021). "As tumor deaths depend on the transportation of proteins with the help of TAP1, it is important to know the expression analysis of TAP1 in the cancer cells." (PMID 34047812, 2021). "TAP1 plays a role in tumor development and resistance to treatment mainly by affecting tumor immune infiltration." (PMID 34957213, 2021). "The data was extracted from TCGA, where we inquired in 33 tumor types paired with their normal samples for the mRNA expression of TAP1." (PMID 34047812, 2021). "ENT treatment led to increased expression of ciita, tap1, tap2, cd74, and major histocompatibility genes—involved in antigen processing and presentation—suggesting an increased ability to T cells to engage tumor cells, consistent with previous reports." (PMID 33369199, 2021). "More importantly, the expression of MHC I, CD40 and TAP1 in DCs in GL-261 LGALS9−/− tumor-bearing mouse CSF was significantly higher than that in DCs in GL-261 WT tumor-bearing mouse CSF." (PMID 33093453, 2020). "In this database, TAP1 levels (achieved from RNA sequencing) were available for 480 tumors and 42 tumor-free samples, showing significantly higher TAP1 levels in tumors (p < 0.001)." (PMID 32867395, 2020). "The results showed an inverse correlation between TAP1 and the previous results on cytolytic activity in clinically tumor-free tongue contralateral to the SCCOT in relation to prognosis." (PMID 32867395, 2020).
tumor (continued). "Nor was there a difference in overall survival between TAP1-low and TAP1-high patients when considering the 479 out of 480 tumor samples with follow-up data available from the TCGA dataset." (PMID 32867395, 2020). "TAP1 levels were also higher in SCCOT (N = 121) compared to tumor-free controls (N = 12, p < 0.001)." (PMID 32867395, 2020). "The results showing that TAP1 levels in tumor-free tongue tissue contralateral to the SCCOT correlate with survival is an important contribution to early diagnosis and follow up of SCCOT." (PMID 32867395, 2020). "Fhit-transfected B11 tumor cells had increased transcriptional levels of the following genes: Fhit, H-2 class I heavy chains, β2-microglobulin, Tap-1, Tap2, LMP2, LMP10, Tapasin, calreticulin, Erap1, ERp57, PA28α, Ttp1, and Ttp2." (PMID 32545680, 2020). "The results showed that TAP1 levels in tumor-free samples remained significant as an independent prognostic factor for overall (p = 0.031) and disease-free survival (p = 0.005)." (PMID 32867395, 2020). "Functional data on mouse tumour cells support an independent role for Tap1 in cytotoxic T lymphocyte‐mediated lysis and reduction in brain metastasis." (PMID 33128234, 2020). "Unexpectedly in our study, we found a gradual increase in TAP1 levels from healthy control to tumor-free to tumor samples." (PMID 32867395, 2020). "Analysis of previously published microarray results showed that TAP1 mRNA is significantly upregulated in tumor-free tongue compared to healthy controls (fold change = 1.65), and further upregulated in tumor samples." (PMID 32867395, 2020). "Dividing patients into TAP1-high and TAP1-low groups according to the median TAP1 level in tumor-free samples showed that patients with lower TAP1 mRNA levels in tumor-free samples had better overall (p = 0.003) and disease-free survival (p = 0.002)." (PMID 32867395, 2020). "Tap1, Tap2, and β2M genes were also upregulated, which are involved in natural killer cell recognition, and tumor cell processing of antigens and presentation through MHC I to cytotoxic CD8+ T cells." (PMID 30718505, 2019). "We also demonstrated that re-introducing IL-33 into metastatic murine tumours increases expression of antigen processing components including TAP-1 and MHC-I surface expression and augments cytotoxic T cell (CTL) immune recognition." (PMID 29440650, 2018). "Accordantly, further downregulation of TAP1 in IGR-Heu tumour cells using specific siRNA induced a decrease in the lytic activity of ppCT9–17 epitope-specific CTLs." (PMID 30504837, 2018). "Several of these genes, including IFI27, IFITM1, IRF1, STAT1, IF16, and TAP1, are known to possess potent anti-proliferative and tumor suppressive properties." (PMID 29176033, 2017). "We suppose that silencing of TAP1 expression provides tumor cells with a mechanism to escape cytotoxic T-lymphocyte recognition." (PMID 26735690, 2016). "The transporter protein associated with antigen processing-1 (TAP1) is part of the MHC class I peptide-loading complex, and important for antigen presentation in tumor and antigen presenting cells." (PMID 26735690, 2016). "It seems reasonable to suppose that TAP1 downregulation provides tumor cells with a mechanism to escape cytotoxic T-lymphocyte recognition explaining ineffectiveness of specific vaccination strategies." (PMID 26735690, 2016). "Loss or down-regulation of proteins involved in antigen processing and presentation, such as HLA class I and TAP1, are well known mechanisms of tumor resistance to CTL attack." (PMID 27484791, 2016). "We further evaluated the association between the risk of genotypes of TAP1 and risk of HPV-associated ESCC stratified by tumor depth." (PMID 26205887, 2015). "There are several studies on the relationship between TAP (including TAP1 and TAP2) polymorphisms and various carcinoma, and only TAP1 polymorphisms have been confirmed to be susceptible to various tumor types." (PMID 26205887, 2015).